SNORA79B (small nucleolar RNA, H/ACA box 79B)
Gene: Small nucleolar RNA gene on chromosome 14 (20,323,179 to 20,323,326, reverse strand). Ensembl gene ENSG00000222489.
Gene Ontology:
Biological process: RNA processing
Cellular component: nucleolus
Homologues: Orthologues: chimpanzee SNORA79B (99% identical), macaque SNORA79B (99% identical), rabbit SNORA79B (90% identical), tropical clawed frog SNORA79B (69% identical). Paralogues in human: SNORA79 (65% identical).